ANXA2R (annexin A2 receptor)
Description:
May act as a receptor for annexin II on marrow stromal cells to induce osteoclast formation.
Synonyms: AXIIR; AX2R; C5orf39
Tractability: No criterion of Open Targets' tractability assessment is met for any kind of drug.
Gene: Protein-coding gene on chromosome 5 (43,039,233 to 43,043,170, reverse strand). Ensembl gene ENSG00000177721.
Subcellular location (Human Protein Atlas): Nucleoplasm; Cytoplasmic bodies; Cytosol
Gene Ontology:
Molecular function: protein binding; signaling receptor activity
Genetic constraint (gnomAD): Missense variants: 145 observed, 153.17 expected, observed/expected ratio (o/e) 0.95, 90% interval 0.83 to 1.09. Synonymous variants: 55 observed, 61.41 expected, observed/expected ratio (o/e) 0.9, 90% interval 0.72 to 1.12.
Homologues: Orthologues: chimpanzee ANXA2R (99% identical).
Diseases named in the same sentence as ANXA2R in open-access papers:
ANXA2R is named in the same sentence as 9 diseases in open-access papers, as found by Europe PMC text mining. Sharing a sentence is not in itself a finding about the gene and the disease. The quoted sentences say what the papers report.
prostate carcinoma (5 papers, 2018 to 2021). A carcinoma that arises from epithelial cells of the prostate gland. "Annexin A2 (ANXA2)/annexin A2 receptor (ANXA2R) interactions between osteoblasts or endothelial cells and circulating prostate cancer cells have also been reported to support homing and adhesion to bone." (PMID 34831167, 2021). "Prostate cancer cells express annexin A2 receptor (ANXA2R), which binds to annexin A2 (ANX2A) that is expressed by bone cells." (PMID 31753020, 2019). "In cases involving prostate cancer cells, the ANXA2/ANXA2R axis and the GAS6-AXL interaction, which both induce dormancy of cancer cells in the bone microenvironment, may represent rational targets for the therapy of skeletal metastasis." (PMID 34831167, 2021).
glioma (2 papers, 2021 to 2022). A benign or malignant brain and spinal cord tumor that arises from glial cells (astrocytes, oligodendrocytes, ependymal cells). "Relative to normal human astrocytes, the expression of ANXA2R in those cells was elevated only in patient-derived WG4 glioma cells; while FOXM1 expression was significantly elevated in 4 out of 5 cell lines." (PMID 34131149, 2021). "Such mapping can be very useful in studying biological mechanisms operating in gliomas of different grades, as exemplified in our analysis of the ANXA2R enhancer." (PMID 34131149, 2021). "The expression of FOXM1 and ANXA2R RNA-seq profiles showed a strong correlation between our samples and in 299 independent TCGA glioma samples." (PMID 34131149, 2021). "We demonstrate that both migration and invasion of glioma cells were significantly reduced in FOXM1-depleted cells with downregulated ANXA2R expression." (PMID 34131149, 2021). "For further studies we have selected WG4 glioma cells due to the highest ANXA2R and FOXM1 expression in those cells." (PMID 34131149, 2021). "We demonstrate that both migration (as tested in a scratch assay) and invasion of glioma cells (tested in a Matrigel assay) were significantly reduced in FOXM1-depleted cells with downregulated ANXA2R expression." (PMID 34131149, 2021). "Expression of ANXA2R has been shown to correlate inversely with prognosis of glioma patients." (PMID 35875673, 2022). "Comparison of FOXM1 and ANXA2R RNA-seq profiles showed a highly significant positive correlation between their expression levels in 33 samples from our cohort and in 299 TCGA glioma samples." (PMID 34131149, 2021). "Altogether, these results support the hypothesis of functional interactions between FOXM1 and the ANXA2R regulatory regions in glioma pathogenesis." (PMID 34131149, 2021).
breast carcinoma (1 paper, 2025). "Cathepsin F can mediate the effects of ANXA2R and ZNF605 on in situ breast cancer." (PMID 39944834, 2025). "We found that ANXA2R protects against in situ breast cancer by reducing the expression of cathepsin F. PRX and CRY2 are protective factors for both cathepsin Z and in situ breast cancer." (PMID 39944834, 2025).
cancer (3 papers, 2021 to 2024). A tumor composed of atypical neoplastic, often pleomorphic cells that invade other tissues. "Among these genes, ANXA2R (Annexin A2 Receptor), RBM3 (RNA-binding Protein 3), and SUCLG2 (Succinyl-CoA ligase [GDP-forming] subunit β), which may act as cancer drivers, were downregulated." (PMID 39766901, 2024).
tumor (2 papers, 2020). "Literature evidences that ANXA2/ANXA2R exerts an important role both in the bone physiology and in the growth of tumor cells in the skeletal tissue." (PMID 32197509, 2020). "In turn, PCa cells express the ANXA2 receptor (ANXA2R), hence this might increase the migratory capacity of tumor cells to the bone." (PMID 32197509, 2020).
ANXA2R also shares sentences with these, for which no sentence is quoted: glioblastoma (1 paper); hepatocellular carcinoma (1); myeloma (1); situ breast cancer (1).